MDM2 (MDM2 proto-oncogene)
Diseases named in the same sentence as MDM2 in open-access papers (continued):
Sharing a sentence is not in itself a finding about the gene and the disease.
liposarcoma (continued). "Dedifferentiated/well-differentiated liposarcomas had a preponderance of MDM2 and CDK4 mutations." (PMID 28424409, 2017). "In our study, 3D-cultured cancer cells preserved both MDM2 amplification and gene expression associated with liposarcoma pathogenesis and aggressiveness, suggesting that this in vitro model could facilitate the identification of disease-specific biomarkers." (PMID 27895047, 2017). "Notably, our case excluded DICER1 mutations (associated with pediatric central nervous system tumors), EWSR1 rearrangements (a hallmark of Ewing sarcoma), and MDM2 amplification (common in liposarcoma and osteosarcoma), highlighting the molecular distinctiveness of HGMS." (PMID 40242239, 2025). "Currently, anti-MDM2 drugs are in the developmental phase, undergoing clinical trials with promising results, especially for tumors that are inoperable, advanced, metastatic, aggressive, and associated with a poor prognosis, such as dedifferentiated liposarcoma (DDLPS), for instance." (PMID 38275873, 2024). "Immunohistochemistry showed positivity for CDK4 and MDM2, and fluorescence in situ hybridization confirmed MDM2 amplification, leading to a diagnosis of atypical lipomatous tumor/well‐differentiated liposarcoma." (PMID 40416586, 2026). "Immunohistochemical analysis revealed positive expression of MDM2, a liposarcoma marker, along with Vimentin, ER, PR, and Ki67, while HER-2 and PCK were negative." (PMID 41518587, 2026). "Functionally, PRL not only enhanced liposarcoma cell and fibrosarcoma cell proliferation but also conferred resistance to MDM2 inhibitors." (PMID 42083506, 2026). "In this study, MDM2 protein expression was detected in both primary tumor tissue and murine xenograft liposarcoma tissue, as well as in the CMLPS-N1 cell line." (PMID 41518587, 2026). "Fluorescence in situ hybridization confirmed MDM2 amplification, leading to a diagnosis of dedifferentiated liposarcoma." (PMID 41509081, 2026). "Therefore, MDM2 IHC staining may serve as a valuable diagnostic marker for canine liposarcomas." (PMID 41518587, 2026). "Well- and dedifferentiated liposarcoma (WDLPS/DDLPS) frequently harbour MDM2 ampflications, likewise useful upon LB." (PMID 39797974, 2025). "Performing MDM2-FISH analysis on a mesenchymal spindle cell tumor in the abdomen or the retroperitoneum is essential for the definitive exclusion of liposarcoma." (PMID 40211332, 2025). "For instance, CDK4/CDK6 inhibitors (e.g., palbociclib) and MDM2 antagonists are under active investigation in clinical trials for advanced liposarcoma." (PMID 41488879, 2025). "For instance, the evaluation of CDK 4, MDM2 and RB-1 expression along with Ki67 has shown potential in distinguishing tumors from different prognostic categories, guiding personalized care in liposarcoma management." (PMID 40870476, 2025). "The needle biopsy specimen showed scattered CDK4‐positive cells in the background of the lymphoma cells and sporadic MDM2 signal amplification on fluorescence in situ hybridization, suggesting mixed well‐differentiated liposarcoma (WDL)." (PMID 39894788, 2025). "Our one case out of 43 (2.3 %) spermatic cord lipoma cases that showed MDM2 gene amplification by FISH compatible with well-differentiated liposarcoma occurred in an older male, 72 years old, and had a size larger than 10 cm (11 cm in maximum dimension)." (PMID 40799874, 2025). "For example, the identification of fusion genes such as EWSR1-FLI1 in Ewing sarcoma, SYT-SSX in synovial sarcoma, and amplification of MDM2 in liposarcoma have already reshaped classification and guided targeted therapy approaches." (PMID 40427203, 2025).
liposarcoma (continued). "In a well-differentiated liposarcoma, the most prominent molecular feature is gene amplification in the 12q13–15 chromosomal region, with MDM2 and CDK4 identified as the principal driver genes." (PMID 41179691, 2025). "As this finding is merely based on cell-based assay findings, in vivo and clinical experiments should be conducted to confirm if miR-215-3p can increase MDM2 expression to accelerate liposarcoma development." (PMID 39736850, 2025). "The frequency of MDM2 amplification varies between nearly 100% in well-/de-differentiated liposarcomas and 0.23% in adenocarcinomas of the appendix." (PMID 41299419, 2025). "The identification of MDM2, CDK 4, and DDIT3 expression is useful in confirming liposarcomas associated with the subsequent genetic alteration, while analysis of Ki67 expression is useful for determining the mitotic index and tumor grade." (PMID 40870476, 2025). "The diagnosis of liposarcoma was further supported by positive immunohistochemical staining for MDM2 and CDK4, which are established markers of this neoplasm." (PMID 39974236, 2025). "Fibroblast growth factor receptor substrate 2 (FRS2), located near MDM2 on chromosome 12q13-15, has a biological role and prognostic value in liposarcoma, which remain to be fully explored." (PMID 40225873, 2025). "Dedifferentiated liposarcoma arises from well-differentiated components, is typically observed at the periphery of the lesion, and is characterized by mouse double minute 2(MDM2) gene amplification." (PMID 41293148, 2025). "In this study, we have studied the use of MDM2 amplification by FISH to differentiate a benign lipoma of cord from well-differentiated liposarcoma, as this difference is crucial in prognosis and treatment." (PMID 40799874, 2025). "Genetically, atypical lipomatous tumors/well-differentiated liposarcomas commonly exhibit amplification of the 12q13-q15 region, which encompasses the MDM2 and CDK4 genes." (PMID 40898472, 2025). "In one study, researchers compared the performance of MDM2 immunohistochemistry (IHC) in inflammatory well-differentiated liposarcoma (WDLS/ALT) with that in fibroinflammatory diseases (such as sclerosing mesenteritis and idiopathic retroperitoneal fibrosis)." (PMID 40308488, 2025). "Despite this low yield, these findings prove the efficacy of MDM2 FISH in diagnosing well-differentiated liposarcoma in the setting of atypical spermatic cord lipoma specimens." (PMID 40799874, 2025). "FISH testing was positive for MDM2, confirming the diagnosis of ovarian-origin dedifferentiated liposarcoma." (PMID 41450911, 2025). "This is line with other publications indicating that pleomorphic liposarcoma is more aggressive with higher risk of metastases compared to conventional well or dedifferentiated liposarcoma with MDM2 amplification." (PMID 40714667, 2025). "Cases with a prior history of spermatic cord well-differentiated liposarcoma with positive MDM2 amplification were excluded." (PMID 40799874, 2025). "Tumor cells do not express epithelial (CK), myogenic (desmin, SMA), neurogenic (CD56, NSE) markers, well-differentiated/dedifferentiated liposarcoma markers (MDM2, CDK4, p16), or solitary fibrous tumor (SFT) markers (β-catenin, STAT6)." (PMID 41458523, 2025). "In well-differentiated and dedifferentiated liposarcomas, MDM2 amplification is frequently observed." (PMID 40075735, 2025). "In solid tumors, responses have generally been modest, with the most compelling benefit seen in well-/dedifferentiated liposarcoma (WD/DD-LPS), where MDM2 amplification on chromosome 12q15 is nearly universal and frequently co-occurs with CDK4 amplification." (PMID 41170373, 2025). "Fluorescence in situ hybridization (FISH) for MDM2 amplification can be used to distinguish between lipomas, atypical lipomas, and well-differentiated liposarcomas." (PMID 40385582, 2025).
liposarcoma (continued). "Immunohistochemically, well-differentiated and dedifferentiated liposarcomas are positive for MDM2 and CDK4." (PMID 40002892, 2025). "One center (H) used no criteria but instead recommended biopsy for all lesions for mouse double minute 2 homolog (MDM2) analysis to differentiate atypical lipomatous tumors/well-differentiated liposarcomas from lipoma." (PMID 40515886, 2025). "MDM2 gene amplification status is considered the gold standard for diagnosis of well-differentiated/dedifferentiated liposarcomas." (PMID 38734790, 2025). "Dedifferentiated liposarcoma arises from a well-differentiated component, which is seen almost focally at the edge of the lesion, and carries MDM2 gene amplification." (PMID 40725486, 2025). "Well-differentiated liposarcoma is characterized by variation in adipocyte size, atypical hyperchromatic nuclei of adipocytes and stromal cells, and up-regulation of MDM2 and/or CDK4." (PMID 40002892, 2025). "For instance, dedifferentiated liposarcoma was frequently diagnosed in patients with poor prognosis, and researchers have acknowledged this peculiarity is related to MDM2 and HMGA2 expression." (PMID 40870476, 2025). "Fibrovascular polypNote 1Note 1: As some of these tumors have chromosomal abnormalities or amplifications of the MDM2 gene, they should be recognized as neoplasms and differentiated from liposarcomas." (PMID 38512393, 2024). "Conversely, if a tumor is located in the head and neck or in an atypical liposarcoma location and shows MDM2 amplification, the possibility of a neoplasm with GLI1 alteration should be systematically ruled out." (PMID 38275873, 2024). "The immunohistochemical expression of MDM2 in canine liposarcoma has been reported, and similar to what is described in people it was interpreted as suggestive of gene amplification." (PMID 38890407, 2024). "Our patient’s diagnosis of liposarcoma was based on the presence of translocation of the MDM2 gene by FISH and IHC on the biopsy and the resected specimens, respectively." (PMID 39252749, 2024). "Advances in molecular biology offer promising avenues for personalized therapy, with potential targets such as CDK4 and MDM2 in well-differentiated and dedifferentiated liposarcomas." (PMID 39347341, 2024). "In these particular cases, two patients initially diagnosed with leiomyosarcoma were reclassified as having dedifferentiated liposarcoma, leading to a change in their treatment approach to include investigational MDM2 or CDK4 inhibitors." (PMID 38228904, 2024). "In this study, MDM2 amplification status was assessed for the first time in canine liposarcoma using FISH." (PMID 38890407, 2024). "All samples retained liposarcoma characteristic, such as high level of MDM2 protein expression and MDM2 DNA amplification after being cultivated in 3D." (PMID 38500686, 2024). "A study of dedifferentiated liposarcoma found that high levels of MDM2 amplification (>38 copies) and CDK4 amplification (>30 copies) were correlated with reduced disease-free survival (DFS) and disease-specific survival (DSS)." (PMID 38275873, 2024).
liposarcoma (continued). "Romidepsin is one example, which showed efficacy in dedifferentiated liposarcoma through suppression of (MDM2) expression and cell death enhancement, and Valproate is another inhibitor, which demonstrated some response in endometrial stromal sarcoma." (PMID 38730621, 2024). "The diagnosis of dedifferentiated liposarcoma was based on histology and MDM2 and/or CDK4 immunohistochemistry findings." (PMID 39839837, 2024). "Sarcomas that exhibit the highest percentages of MDM2 amplification include low-grade/periosteal osteosarcoma, atypical liposarcoma/lipomatous tumor, dedifferentiated liposarcoma, and intimal sarcoma." (PMID 38275873, 2024). "Well-differentiated and dedifferentiated human liposarcomas are characterized by the presence of a giant ring chromosome that carries amplified copies of the MDM2 and CDK4 genes, which play essential roles in cell cycle regulation." (PMID 38890407, 2024). "In these situations, the presence of well-differentiated liposarcoma, confirmed MDM2 and CDK4 expression by immunohistochemistry, or amplification by FISH would strongly support the diagnosis of dedifferentiated liposarcoma." (PMID 38388450, 2024). "The MDM2 inhibitor brigimadlin remains under clinical evaluation and has shown objective responses for patients with MDM2-amplified well-differentiated liposarcoma as well as prolonged stable disease for patients with dedifferentiated liposarcoma." (PMID 39510293, 2024). "This case initially suggested dedifferentiated liposarcoma with smooth muscle differentiation due to strong MDM2 and CDK4 positivity." (PMID 38993816, 2024). "Whereas liposarcoma is a malignant adipocytic soft tissue tumor and can be differentiated from its benign counterpart by a positive MDM2 amplification on fluorescence in situ hybridization (FISH)." (PMID 38740577, 2024). "Based on the immunohistochemical staining findings of MDM2, a left inguinal dedifferentiated liposarcoma and primary pulmonary unclassified sarcoma were diagnosed." (PMID 39466487, 2024). "The efficacy of increasing doses of MDM2 inhibitor SAR405838 on our liposarcoma cell lines was already reported, the aim of this assessment was to investigate how our Collagen 3D models were affected by the drug treatment." (PMID 38500686, 2024). "MDM2 (whose full-length corresponds to 90 kDa) was detected in all samples for both cell lines, supporting the idea that MDM2 amplification, the main dedifferentiated liposarcoma feature, was still preserved in 3D cultures." (PMID 38500686, 2024). "Well-differentiated (WDLPS) and dedifferentiated (DDLPS) liposarcoma are the most frequent subtypes of RPLPS and present amplified MDM2 gene as a hallmark." (PMID 39769278, 2024). "Such genetic aberrations are often associated with amplification of oncogenes like MDM2 and CDK4, which are crucial in the development and progression of well-differentiated and dedifferentiated liposarcomas." (PMID 39229483, 2024). "In fact, liposarcomas are defined by amplification of MDM2, which is frequently co-amplified with its genomic neighbor CDK4/6." (PMID 36980578, 2023). "MDM2 is reported as an oncogene and driver alteration of liposarcoma, being coherently amplified in DDLPS expression data." (PMID 37834179, 2023). "For example, ALT/WDLS and dedifferentiated liposarcoma are types of tumors known for their distinct genetic characteristics, particularly the amplification of the mouse double minute 2 (MDM2) oncogene on the 12q13-15 region." (PMID 38132190, 2023). "In this review, all patients receiving MDM2 inhibitors had liposarcomas, with a treatment response of SD or better, including one CR." (PMID 37240900, 2023). "Another MDM2 inhibitor molecule BI907828 has been found effective in xenograft models carrying patient-driven MDM2 rich dedifferentiated liposarcoma." (PMID 37314603, 2023).
liposarcoma (continued). "The efficacy of CDK4 inhibitors such as palbociclib and abemaciclib in advanced liposarcoma with MDM2/CDK4 amplification is modest in early trials and real-world settings, suggesting a cytostatic rather than cytotoxic effect." (PMID 36652666, 2023). "In some types of cancer, such as liposarcoma and osteosarcoma, the MDM2 gene can become amplified, leading to an overproduction of the MDM2 protein." (PMID 37297833, 2023). "When used alone or in combination with CDK4, they significantly reduced tumour growth in liposarcomas with amplified MDM2, as reported in a Phase I clinical trial." (PMID 37681936, 2023). "In this study, 22 of the 53 patients with dedifferentiated liposarcoma were confirmed to have MDM2 amplification or overexpression." (PMID 36980578, 2023). "The clinical trial “Brightline-1: A Study to Compare BI 907828 With Doxorubicin in People With a Type of Cancer Called De-differentiated Liposarcoma” is testing another MDM2 inhibitor versus doxorubicin chemotherapy." (PMID 37298520, 2023). "All samples with MDM2 amplifications were classified under the methylation class of ‘well/dedifferentiated liposarcoma’ (WDLS/DDLS), characterized by MDM2 amplification." (PMID 37627196, 2023). "Targeting CDK4 seemed particularly attractive for WDLPS and DDLPS, in which it has a specific clinical and biological significance, with respect to MDM2 amplified-only liposarcomas." (PMID 36741019, 2023). "We retrospectively retrieved 51 liposarcomas, 25 Lipomas, 5 Spindle Cell Lipoma/Pleomorphic Lipomas, and 2 Atypical Spindle Cell Lipomatous Tumors and the corresponding MDM2 FISH analysis." (PMID 36674856, 2023). "Based on these data and published evidence in the literature, we propose a set of criteria to guide MDM2 amplification analysis in liposarcoma." (PMID 36674856, 2023). "In de-differentiated liposarcoma, MDM2 is amplified in all tumors while in other tumors such as extraskeletal osteosarcoma MDM2 amplification is found in about 40% of the tumors." (PMID 37627196, 2023). "Histological examination revealed a mature adipocyte neoplasm whose morphological and molecular characteristics (amplification of the MDM2 gene) are consistent with the diagnosis of dediferrentiated liposarcoma variety CO-MINGLED, G2 (sec." (PMID 37680656, 2023). "All patients receiving MDM2 inhibitors were patients with liposarcoma and MDM2 amplification; furthermore, all patients had a treatment effect of SD or better with a treatment duration ranging from 4 to 83 months." (PMID 37240900, 2023). "In this study, we identified that the MDM2 biomarker is more accurate for the diagnosis of ALT/WDLS than for the diagnosis of liposarcoma." (PMID 38132190, 2023). "A number of clinical trials targeting MDM2 are ongoing for patients with advanced de-differentiated liposarcoma." (PMID 37298520, 2023). "Expected disease-defining gene alterations were detected in several histological subtypes, including MDM2 and CDK4 in liposarcoma, IDH mutations in chondrosarcoma, and alterations related to tyrosine kinases in GIST (KIT, PDGFR)." (PMID 37542550, 2023). "In preclinical studies, BI907828 showed excellent activities in de-differentiated liposarcoma xenografts carrying MDM2 amplification." (PMID 37298520, 2023). "MDM2 FISH was performed, which revealed MDM2 gene amplification, leading to the diagnosis of a well-differentiated liposarcoma with myxoid and inflammatory morphology." (PMID 38137051, 2023). "These panels should include a variety of makers to ensure accurate diagnosis, as seen by the presence of TLE1 in synovial sarcoma or MDM2 in liposarcoma." (PMID 38156143, 2023). "This assumption is supported by the fact that patients with dedifferentiated liposarcoma characteristically carry MDM2 (and CDK4/6) amplifications and novel MDM2 inhibitors are tested in the first-line setting (NCT05218499)." (PMID 37542550, 2023).